WFDC6 (WAP four-disulfide core domain 6)
Synonyms: C20orf171; WAP6; dJ461P17.11; HEL-S-295
Tractability: Antibody: UniProt places it where antibodies can reach, with high confidence; UniProt predicts a signal peptide or a membrane-spanning region; its Gene Ontology location is reachable by antibodies, with medium confidence.
Gene: Protein-coding gene on chromosome 20 (45,534,196 to 45,539,482, reverse strand). Ensembl gene ENSG00000243543.
Subcellular location: Secreted
Genetic constraint (gnomAD): Loss-of-function variants: 10 observed, 9.26 expected, observed/expected ratio (o/e) 1.08, 90% interval 0.66 to 1.75. That is too few expected variants to judge how well the gene tolerates losing a copy. Missense variants: 105 observed, 111.1 expected, observed/expected ratio (o/e) 0.95, 90% interval 0.81 to 1.11. Synonymous variants: 28 observed, 39.11 expected, observed/expected ratio (o/e) 0.72, 90% interval 0.53 to 0.98.
Homologues: Orthologues: macaque WFDC6 (85% identical), Caenorhabditis elegans Y55F3BR.2 (20% identical), tropical clawed frog spint1 (16% identical), zebrafish spint1a (16% identical), Caenorhabditis elegans mlt-11 (15% identical), Caenorhabditis elegans T21D12.7 (14% identical), zebrafish lrp11 (13% identical), zebrafish spint1b (13% identical), zebrafish wfikkn1 (13% identical), Caenorhabditis elegans tag-290 (12% identical), Drosophila melanogaster CG7565 (12% identical), zebrafish si:dkeyp-73b11.8 (12% identical), and 7 more. Paralogues in human: EPPIN (47% identical), WFIKKN1 (22% identical), WFIKKN2 (21% identical), KIAA0319 (15% identical), LRP11 (15% identical), AMBP (14% identical), KIAA0319L (14% identical), SPINT1 (14% identical), TFPI (13% identical), TFPI2 (12% identical), SPINT4 (8% identical), WFDC8 (8% identical), and 1 more.
Diseases named in the same sentence as WFDC6 in open-access papers:
WFDC6 is named in the same sentence as 2 diseases in open-access papers, as found by Europe PMC text mining. Sharing a sentence is not in itself a finding about the gene and the disease. The quoted sentences say what the papers report.
cancer (1 paper, 2024). A tumor composed of atypical neoplastic, often pleomorphic cells that invade other tissues. "Overall, there was an increase in the TR (e.g., WFDC6, GATS, FMNL3, COQ4, and MEOIC) as the cancer stage progressed, whereas a decrease in the TR was noted for PARVA." (PMID 39349823, 2024).
WFDC6 also shares sentences with these, for which no sentence is quoted: breast carcinoma (1 paper).